ATF5 (activating transcription factor 5)
Diseases named in the same sentence as ATF5 in open-access papers (continued):
Sharing a sentence is not in itself a finding about the gene and the disease.
psychiatric disorder (2 papers, 2017 to 2021). A disorder characterized by behavioral and/or psychological abnormalities, often accompanied by physical symptoms. "In this regard, investigations of the mechanisms underpinning the behavioural abnormalities exhibited by ATF5−/− mice may shed light on human psychiatric disorders." (PMID 33790322, 2021). "Our findings indicated that impairment of ATF5 function may be involved in the pathogenesis of psychiatric disorders." (PMID 28744205, 2017). "Taken together, these findings suggest that ATF5-/- mice may be a unique animal model of some psychiatric disorders." (PMID 28744205, 2017). "Further study of ATF5-/- mice may yield novel therapeutic strategies for the treatment of these psychiatric disorders." (PMID 28744205, 2017). "ATF5−/− mice may therefore be a useful animal model for psychiatric disorders." (PMID 33790322, 2021). "Therefore, ATF5−/− mice may be considered a useful model for studying the pathology of psychiatric disorders." (PMID 33790322, 2021).
mitochondrial disease (1 paper, 2025). "The response in QFs supports this conclusion: fasting‐related metabokine FGF21 is secreted to blood circulation as part of their ATF5‐driven ISRmt response to mitochondrial disease." (PMID 40681476, 2025).
myopathy (1 paper, 2022). A disease of the muscle in which the muscle fibers do not function properly. "Whether ATF3 or ATF5 plays a role in myopathy is also not understood, though ATF5 loss did not affect the response of HeLa cells to mitochondrial dysfunction." (PMID 35531957, 2022).
ATF5 also shares sentences with these, for which no sentence is quoted: anaplastic gliomas (2 papers); B-cell lymphoma (2); fibrosarcoma (2); prostate carcinoma (2); acute kidney injury (1); astrocytomas (1); autoimmune disease (1); bipolar disorder (1); Cerebral ischemia (1); childhood acute lymphoblastic leukemia (1); ciliopathies (1); cognitive deficits (1); colorectal cancer (1); cutaneous T cell lymphoma (1); deafness (1); delirium (1); Depression (1); diabetic kidney disease (1); epithelioid hemangioendothelioma (1); follicular lymphoma (1); genetic disorder (1); heart disease (1); hemangioendothelioma (1); hookworm infection (1); hypertrophic cardiomyopathy (1); intervertebral disc degeneration (1); liver inflammation (1); medulloblastoma (1); MELAS (1); neurological disease (1).
A further 9 diseases each share a sentence with ATF5 in 1 paper.